IGHV3-20 (immunoglobulin heavy variable 3-20)
Description:
V region of the variable domain of immunoglobulin heavy chains that participates in the antigen recognition. Immunoglobulins, also known as antibodies, are membrane-bound or secreted glycoproteins produced by B lymphocytes. In the recognition phase of humoral immunity, the membrane-bound immunoglobulins serve as receptors which, upon binding of a specific antigen, trigger the clonal expansion and differentiation of B lymphocytes into immunoglobulins-secreting plasma cells. Secreted immunoglobulins mediate the effector phase of humoral immunity, which results in the elimination of bound antigens. The antigen binding site is formed by the variable domain of one heavy chain, together with that of its associated light chain. Thus, each immunoglobulin has two antigen binding sites with remarkable affinity for a particular antigen. The variable domains are assembled by a process called V-(D)-J rearrangement and can then be subjected to somatic hypermutations which, after exposure to antigen and selection, allow affinity maturation for a particular antigen.
Synonyms: IGHV320; VH
Gene: Immunoglobulin variable (V) gene on chromosome 14 (106,210,936 to 106,211,453, reverse strand). Ensembl gene ENSG00000211946.
Subcellular location: Secreted; Cell membrane
Gene Ontology:
Molecular function: antigen binding
Biological process: immunoglobulin mediated immune response
Cellular component: extracellular region; plasma membrane
Homologues: Paralogues in human: IGHV3-43 (89% identical), IGHV3-74 (86% identical), IGHV3-23 (85% identical), IGHV3-11 (85% identical), IGHV3-66 (84% identical), IGHV3OR16-10 (84% identical), IGHV3-48 (83% identical), IGHV3-64 (83% identical), IGHV3-7 (83% identical), IGHV3OR16-13 (83% identical), IGHV3-21 (82% identical), IGHV3-53 (82% identical), and 65 more.